CFHR5 (complement factor H related 5)
Diseases named in the same sentence as CFHR5 in open-access papers (continued):
Sharing a sentence is not in itself a finding about the gene and the disease.
Hypertension (1 paper, 2023). The presence of chronic increased pressure in the systemic arterial system. "Higher plasma CFHR5 levels were associated with severe histological features, proteinuria, hypertension, and reduced eGFR in IgAN." (PMID 37020564, 2023).
injury (1 paper, 2021). Damage inflicted on the body as the direct or indirect result of an external force, with or without disruption of structural continuity. "Existing studies have not found an association with pregnancy-related diseases, but CFHR5 is positively associated with kidney injury." (PMID 33874952, 2021).
lung carcinoma (1 paper, 2023). "The second panel, comprising CFHR5, C9, and MBL2 proteins, shows potential in evaluating the occurrence of metastasis in patients with early-stage lung cancer." (PMID 37953280, 2023).
macular degeneration (1 paper, 2016). Loss of vision in the central portion of the retina (macula), secondary to retinal degeneration. "Interestingly, seven genes associated with macular degeneration (CFH, C3, C2, CFHR5, CFB and CFHR4, CFHR1) also form a statistically significant module in liver (p value < 10−26, z score = 10.85)." (PMID 27748412, 2016).
nephritis (1 paper, 2024). Inflammation of renal tissue. "Here, we report the case of a young woman with C3 nephritis and a heterozygous rare variant, P453S, in CFHR5." (PMID 38558633, 2024).
Obesity (1 paper, 2023). Accumulation of substantial excess body fat. "Complement factor H-related protein 5 (CFHR5) levels were elevated only in obese PCOS compared to controls and were associated with BMI in obese PCOS, suggesting that obesity is responsible for the changes seen." (PMID 37566081, 2023).
otitis media with effusion (1 paper, 2022). Otitis media associated with accumulation of fluid in the middle ear. "Of note, high CFHR5 levels have been observed in otitis media with effusion which was hypothesized to compete with CFH for binding of C3b enabling rapid enhancement of complement activation." (PMID 36194022, 2022).
preeclampsia (1 paper, 2025). Preeclampsia is a hypertensive disorder of pregnancy that is characterized by new-onset hypertension with proteinuria presenting after 20 weeks of gestation, and depending on mild or severe forms may initially present with severe headache, visual disturbances, and hyperreflexia. "Additionally, SAA4, ANG, CFHR5, IGKV3-7, and PAPPA have been suggested to play a role in the context of preeclampsia." (PMID 40974471, 2025).
renal fibrosis (1 paper, 2025). A final common manifestation of a wide variety of chronic kidney diseases characterized by glomerulosclerosis and tubulointerstitial fibrosis. "Among the differentially expressed proteins, THBS1 and CFHR5 emerged as potential markers of renal fibrosis and complement-mediated glomerular injury, while IGFBP3 reflected growth factor dysregulation associated with both renal and cardiac remodeling." (PMID 41301692, 2025).
respiratory failure (1 paper, 2020). The significant impairment of gas exchange within the lungs resulting in hypoxia, hypercarbia, or both, to the extent that organ tissue perfusion is severely compromised. "The variant rs371740347 intronic to CFHR5 was associated with “respiratory failure, insufficiency, arrest” (UK Biobank MAF = 0.01; MAC in cases vs. controls = 81 vs. 6,319; P = 6.9 × 10−5), though the allele increasing FVC was associated with increased risk of this phenotype." (PMID 33057025, 2020).
Sepsis (1 paper, 2024). Sepsis is defined as life-threatening organ dysfunction caused by a dysregulated host response to infection. "By revealing a causal link between sepsis and CFHR5, FCER2, GZMB, HLA-DQA2, MBL2, or MPO, our study offers an essential resource for additional investigations on the subject." (PMID 39252215, 2024).
streptococcal infection (1 paper, 2012). Any of the several infectious disorders caused by members of streptococcus, a genus of gram positive bacteria belonging to the family Streptococcaceae. "We speculate that CFHR5 mutations may be a risk factor for the development of chronic glomerulonephritis after streptococcal infection." (PMID 22503529, 2012).
thrombosis (1 paper, 2023). "On basis of these recently published mechanistic findings, our in vitro results indicate that CFHR5 regulation of the alternative pathway of complement activation has a role in C3a mediated platelet activation in thrombosis, providing a potential functional link to its association with acute VTE." (PMID 37286573, 2023).
infection (7 papers, 2010 to 2024). The state of being infected such as from the introduction of a foreign agent such as serum, vaccine, antigenic substance or organism. "Taken together, we identified complement proteins CFHR2 and CFHR5 as novel ligands for the infection-associated CRASP-4/ErpC protein of B. burgdorferi." (PMID 22400034, 2012). "In summary, we identified two new ligands, CFHR2 and CFHR5 for the infection-associated CRASP-3 and CRASP-5 proteins of B. burgdorferi." (PMID 20975954, 2010). "In this study, we extend the characterization of molecular interaction of CFH/CFHR proteins and show that the infection-associated CRASP-4/ErpC protein of B. burgdorferi binds the host complement regulators CFHR1, CFHR2, and CFHR5, and to some extent CFH." (PMID 22400034, 2012). "Here, we extend the characterization of the infection-associated CRASP proteins, CRASP-3 and CRASP-5 of B. burgdorferi s.s. and show that these two molecules bind the host immune regulators CFHR2 and CFHR5." (PMID 20975954, 2010).
tumor (4 papers, 2020 to 2025). "Additionally, rs215539 (r = 0.501, p = 0.004) in CPXM1, which is associated with tumor progression and immune cell infiltration, and rs1332664 (r = 0.484, p = 0.005) in CFHR5, a gene related to complement regulation, were also significantly associated with general fatigue." (PMID 40462080, 2025).
respiratory diseases (1 paper, 2020). "Receiver operating characteristics analyses using a 5-protein panel (CFHR5, LRG1, CRP, LBP, and SAA1) exhibited discriminatory power in distinguishing TB from other respiratory diseases (AUC = 0.81)." (PMID 32780727, 2020).
CFHR5 also shares sentences with these, for which no sentence is quoted: glomerulopathy (4 papers); dense deposit disease (3); glioblastoma (3); Alport syndrome (2); Fabry disease (2); membranoproliferative glomerulonephritis (2); systemic lupus erythematosus (2); ankylosing spondylitis (1); autosomal-dominant tubulointerstitial kidney disease (1); Blau syndrome (1); cystic fibrosis (1); Dent disease (1); end-stage renal disease (1); focal glomerular sclerosis (1); G6PD deficiency (1); Glomerular sclerosis (1); heart diseases (1); Hematuria (1); Hypoglycemia (1); Immune Complex-Mediated Membranoproliferative Glomerulonephritis (1); inborn error of immunity (1); Insulin resistance (1); joint diseases (1); Lowe syndrome (1); membranous nephropathy (1); Methylmalonic aciduria (1); nephronophthisis (1); pulmonary fibrosis (1); Streptococcus pneumoniae infection (1); thin basement membrane nephropathy (1).